RNU6-244P (RNA, U6 small nuclear 244, pseudogene)
Gene: Small nuclear RNA gene on chromosome 14 (102,501,676 to 102,501,779, forward strand). Ensembl gene ENSG00000212330.
Homologues: Orthologues: chimpanzee U6 (100% identical), macaque U6 (74% identical). Paralogues in human: RNU6-33P (87% identical), RNU6-47P (87% identical), RNU6-1 (86% identical), RNU6-11P (86% identical), RNU6-15P (86% identical), RNU6-2 (86% identical), RNU6-30P (86% identical), RNU6-37P (86% identical), RNU6-3P (86% identical), RNU6-4P (86% identical), RNU6-5P (86% identical), RNU6-6P (86% identical), and 1290 more.